DCX (doublecortin)
Diseases named in the same sentence as DCX in open-access papers (continued):
Sharing a sentence is not in itself a finding about the gene and the disease.
glioma (continued). "A search for glioma datasets revealed that DCX is expressed in a wide range of glioma tissues from different datasets, and further analysis showed higher expression relative to normal tissues." (PMID 32050972, 2020). "Few studies reported that DCX is preferentially expressed at the invasive front of glioma, indicating a pro-invasive role." (PMID 31003495, 2019). "DCX was reported to inhibit glioma invasion in vitro and reduce tumor volume in vivo possibly by inducing apoptosis in tumor stem-like cells, overall indicating that DCX is a tumor suppressor." (PMID 29523123, 2018). "Doublecortin significantly reduces self-renewal of brain tumor stem cells in human primary glioma cells from surgically removed human glioma specimens and glioma cells in vitro and in vivo." (PMID 29285244, 2017). "The SVZ is an active proliferative zone within the brain and this region has previously been shown to be reactive and produce nestin and doublecortin positive neuroblasts in response to glioma." (PMID 25875288, 2015). "For example, DCX is a differentiation-based treatment in vivo for glioma, where DCX induces terminal differentiation of glioma cells via a DCX/GFAP (glial fibrillary acidic protein) pathway." (PMID 26793044, 2015). "Additionally, Transwell and wound healing assays were conducted to evaluate the effect of DCX depletion on glioma cell migration and invasion after exposing cells to TMZ and irradiation." (PMID 39719558, 2024). "As we observed a reduced rate of glioma cell proliferation following DCX knockdown, we explored if apoptosis could be the determinant for this decelerated proliferation." (PMID 39719558, 2024). "In this study, we tested the hypothesis that DCX directly modulates glioma proliferation and apoptosis both in vitro and in vivo." (PMID 39719558, 2024). "Thus, elucidating how DCX influences glioma cell proliferation is pivotal for developing effective therapeutic strategies." (PMID 39719558, 2024). "Collectively, these findings suggest that DCX knockdown may promote glioma cell apoptosis by enhancing the efficacy of TMZ and irradiation therapy." (PMID 39719558, 2024). "Targeting DCX represents a potential therapeutic target for glioma treatment." (PMID 39719558, 2024). "Hence, further clarifications on DCX expression status and functions in gliomas needs to be explored." (PMID 32050972, 2020). "Predictably, the histopathology of GDCX cells in the murine tumor was different from that of the wt-C6 murine glioma tumor; tissues stained with anti-DCX, anti-GFAP, and anti-vimentin antibodies showed a positive correlation with high DCX expression as seen in GDCX tumor." (PMID 32050972, 2020). "Overall, these results establish that DCXNLS2 is crucial for nuclear translocation of DCX in gliomas and may be sufficient for the chain of events leading to DCX translocation." (PMID 32050972, 2020). "DCX translocation improves cellular invasion and proliferation in vitro and in vivo, as overexpression of DCX and inhibition of its translocation to the nucleus respectively promotes or hinders migration and invasion of glioma cells." (PMID 32050972, 2020). "However, detailed reports on the pro-oncogenic functions of DCX in glioma development remains exclusive." (PMID 32050972, 2020). "Moreover, knocking down or blocking DCX nuclear import attenuates invasiveness and proliferation of glioma cells." (PMID 32050972, 2020). "DCX is a neuronal microtubule-associated protein (MAP) that is crucial for adult neurogenesis and neuronal migration and has been associated with poor prognosis in gliomas." (PMID 32050972, 2020). "Furthermore, we explored the mechanism and consequences of DCX nuclear translocation and delineate its preponderance in glioma development." (PMID 32050972, 2020). "Accordingly, the role of DCX in glioma needs to be critically evaluated." (PMID 31003495, 2019). "Consequently, DCX has been used in some studies as a molecular indicator of the infiltrating glioma cells." (PMID 28701917, 2017).
glioma (continued). "Doublecortin is a microtubule-binding protein that induces growth arrest at the G2–M phase of the cell cycle in glioma cells and suppresses tumor xenograft growth in a Spinophilin-dependent manner, which occurs concomitantly with PP1 localization into the cytosol." (PMID 29285244, 2017). "Doublecortin (DCX) plays a crucial role in neuroblast migration and since it was reported that DCX is preferentially expressed in invasive gliomas, the sensitivity and specificity of DCX as a marker for infiltrating glioma cells was immunohistochemically evaluated." (PMID 23284888, 2012). "This confirmed that gliomas with 1p19q codeletion overexpressed neuronal/normal brain genes (AKR1C3, C20orf42, CTTNBP2, L1CAM, GALNT13) as well as genes implicated in gliogenesis and neurogenesis (OLIG2, BMP2, NOG, DCX, ATOH8)." (PMID 18492260, 2008). "Therefore, our studies suggest that DCX is a critical regulator of apoptosis in glioma cells, and may serve as a novel therapeutic target for glioma treatment." (PMID 39719558, 2024). "However, the role of DCX, particularly in regulating the survival and growth of glioma cells, remains unclear." (PMID 39719558, 2024). "DCX expression was observed in grades II glioma tissues in the cohort of glioma samples probed with western blotting (WB) under similar condition, however, slightly higher than the non-neoplastic tissues, but significantly lower compared to high-grade gliomas (III and IV GBM tissues)." (PMID 32050972, 2020). "Third, 1p19q codeleted gliomas were characterized by one specific cluster (gene cluster D) enriched in genes involved in CNS development (6 genes, p < 10-4), which also contained genes known to be specifically expressed in neuronal cells in the physiological state, e.g. DCX and GALNT1." (PMID 18492260, 2008). "To evaluate the early effects of treatment in the population of DCX + neuroblasts in the SVZ, we euthanized glioma-bearing mice at 5 days after initiation of RT + aPD-1 treatment (15 dpi)." (PMID 33658642, 2021). "It confirmed that DCX is explicitly expressed in infiltrating gliomas but not in reactive astrocytes." (PMID 34948016, 2021). "In conclusion, our findings support the notion that glioma cells express DCX; however, there is no clear evidence to prove that DCX participates in GBM cell migration." (PMID 34948016, 2021). "DCX was also reported to be strongly expressed at the invasive front of gliomas regardless of the tissue grade or type, in patients-derived primary or recurrent GBM tumors, or cell lines." (PMID 32050972, 2020). "In another cohort excised at a different time and condition, and in a different set of glioma patients, immunoblotting showed that DCX expression in GBM tissues was higher than in low-grade gliomas and the non-neoplastic tissues." (PMID 32050972, 2020). "Consistent with U251, the time-course immunocytochemical analysis with neuronal markers DCX, TUBB3 and MAP2, showed that ASCL1 alone could also rapidly and efficiently reprogram U87 human glioma cells into neuron-like cells." (PMID 31212628, 2019). "Thus, localization of the doublecortin–Spinophilin–PP1 complex in the cytosol inhibits PP1 phosphatase activity, leading to glioma cell death effects via a mitotic spindle catastrophe." (PMID 29285244, 2017). "By looking into single-cell RNA-seq data, the majority of DCX+ cells were classified as non-cancerous, with a small subset of cells that could be regarded as glioma stem cells." (PMID 34948016, 2021). "In conclusion, our findings support the notion that DCX is indeed expressed by glioma cells, but there is no clear evidence to prove that it may participate in GBM cell migration." (PMID 34948016, 2021). "Furthermore, DCX expression alone may be considered as a poor prognostic marker of GBM, inhibiting DCX nuclear accumulation may weaken the invasive abilities of glioma cells and pave the way for effective delivery of therapeutic interventions." (PMID 32050972, 2020).
Cognitive impairment (19 papers, 2013 to 2025). Abnormal cognition is characterized by deficits in thinking, reasoning, or remembering. "DCX-positive neurons are also disappearing in other neurological conditions, including multiple sclerosis and cognitive impairments." (PMID 40497983, 2025). "The number of doublecortin (DCX)-positive immature neurons in the dentate gyrus decreases in patients with mild cognitive impairment (MCI) and those in the early stages of AD, and is further reduced in later stages." (PMID 38790197, 2024). "It was shown that VPA treatment leads to cognitive impairments and a reduction in cell proliferation in the hippocampus by decreasing doublecortin (DCX) levels." (PMID 36902233, 2023). "For 4 weeks, male Sprague–Dawley rats treated with CPP (25,50 mg/kg/week, i.p) found a long-lasting cognitive impairment with suppression of hippocampal neurogenesis confirmed by decreased doublecortin (DCX)-positive cells in the hippocampal dentate gyrus." (PMID 34643772, 2021). "We examined doublecortin expression in the dentate gyrus of the hippocampus in coronal sections from hAPP mice at 5–7 months of age, when behavioral/cognitive deficits are robust, but before the development of extracellular plaques." (PMID 24244537, 2013). "Similarly, another study found that the number of DCX+ cells was reduced in individuals with mild cognitive impairment." (PMID 40013092, 2025). "While immature DCX+ cells are still present in the dentate gyrus of aged human brains, recent studies have shown that decreased DCX+ cell density in the DG of AD patients is correlated with the severity of the cognitive disorders." (PMID 33519385, 2020). "Melatonin administration was able to increase the protein levels of DCX, suggesting that this indolamine seems to regulate neurogenesis by influencing the proportion of newly generated immature neurons and, consequently, counteracting the cognitive impairment induced by VPA." (PMID 36902233, 2023). "Results of the present study showed a decreased number of DCX+ and Ki67+ neurons in hippocampi in CP/CPPS rats, suggesting that decreased neurogenesis and neuronal proliferation may underlie behavioral changes and cognitive impairment." (PMID 37064799, 2023). "Furthermore, restoring hippocampal APN levels through exercise in STZ-treated mice (which also present AD like cognitive impairments) restores the number of Ki67 and doublecortin (DCX) positive cells and the ratio of co-labeling of DCX as well as bromodeoxyuridine (BrdU) in the DG." (PMID 33653273, 2021). "After 5 weeks of administration, C29 reduced cognitive impairment and restored the expression of key neurogenic and anti-inflammatory markers, including brain-derived neurotrophic factor (BDNF), doublecortin (DCX), and cAMP response element-binding (CREB)." (PMID 40636703, 2025). "Treatment with AAV-sFKN partially restored expression of both Ki67 and DCX in the SGZ, indicative of increased neurogenesis, suggesting that its ability to mitigate cognitive deficits in CX3CL1−/− mice could be dependent on this activity." (PMID 32410624, 2020).
depression (18 papers, 2015 to 2026). "Nevertheless, the impact of DCX expression in the DG on depression has yet to be explored, and its causal relationship with depression-like symptoms needs to be determined in future research." (PMID 39463206, 2024). "Neurogenic biomarkers—including brain-derived neurotrophic factor (BDNF), Ki-67, doublecortin (DCX), and hippocampal volume—have shown consistent associations with depression severity." (PMID 41586064, 2026). "Chronic treatment with the serotonin (5-HT)2C receptor agonist lorcaserin improved depression-like behaviour and concurrently restored the diminished number of DCX+ cells." (PMID 39463206, 2024). "In this context, our earlier study and the present investigation revealed that during protracted nicotine abstinence, rats developed a depression-like phenotype concomitant with a decrease in the number of immature neurons (DCX+) in the DG." (PMID 39463206, 2024). "Accumulated literature has reported that hippocampal neurogenesis exerts an effect on the resistance to depression, so we tested the expression of the neurogenesis marker DCX." (PMID 35719151, 2022). "In a cell model, it also confirmed that miR-139-5p antagonists can promote neurogenesis and ameliorate depression by increasing the number of doublecortin (DCX)-positive cells and new mature neurons." (PMID 35562946, 2022). "We confirmed that NYT improves the decrease in Ki-67 and the number of DCX-positive cells in the hippocampi of corticosterone-induced depression model mice." (PMID 36299904, 2022). "Here, our inducible transgenic mouse with transient reduction in DCX+ cells showed depression-related behaviors." (PMID 26795203, 2016). "We have previously shown that disturbances in the number of doublecortin (DCX, a marker of immature neurons)-positive (DCX+) cells in the dentate gyrus (DG) of the hippocampus during nicotine deprivation may contribute to a depression-like state in rats." (PMID 39463206, 2024). "Furthermore, in depression-like model mice, treatment with ghrelin increased the expression level of DCX." (PMID 34327209, 2021). "DCX+ cells overall tended to increase when cells were treated with TW4 serum compared with TW0 serum; however, patients who developed IFN-α–induced depression had a significantly lower increase in the number of DCX+ cells between TW0 and TW4." (PMID 31207337, 2019). "When entering separately each marker in the model, results show that a lower increase in DCX+ cells between TW0 and TW4 is predictive of later development of depression." (PMID 31207337, 2019). "While serum from all patients increased the number of DCX+ cells and neuronal (MAP2+) cells between TW0 and TW4, patients who developed IFN-α–induced depression had a significantly lower increase in the number of DCX+ cells between TW0 and TW4." (PMID 31207337, 2019). "Secondly, we assessed whether changes in neurogenic (DCX and MAP2) and apoptotic markers (CC3) detected upon treatment with TW4 serum samples were able to predict later depression." (PMID 31207337, 2019). "Serum corticosterone levels, depression-like behavior, and hippocampal pathophysiology, including the expression of brain-derived neurotrophic factor (BDNF), precursor BDNF (proBDNF), doublecortin (DCX), NeuN, glial cell activation, and tumor necrosis factor-α (TNF-α), were examined." (PMID 40361157, 2025). "Although no clear pattern emerged with regards to DCX expression among subjects with a primary diagnosis of depression as compared to those with some other Axis I disorder, it is impossible to confirm with certainty whether additional group differences would emerge with larger sample sizes." (PMID 26082689, 2015). "Notably, patients who developed IFN-α–induced depression had a significantly higher number of apoptotic (CC3+ and CC3/Brdu+) cells at TW0, but not at TW4, and a significantly lower number of neuroblast (DCX+) cells at TW4, but not at TW0." (PMID 31207337, 2019).
neuroblastoma (17 papers, 2008 to 2024). Neuroblastoma (NB) is the most common solid, extracranial childhood tumor. "Doublecortin, a microtubule-associated protein involved in neuronal migration, has recently been proposed as a molecular marker for the detection of minimal residual disease in human neuroblastoma." (PMID 18230156, 2008). "Upregulation of miR-128 reduces cell proliferation by targeting the transcription factor E2F 3a (E2F3a) and Bmi-1 while blocking the Reel and Doublecortin (DCX) promoters reduce neuroblastoma cell migration and metastatic spread." (PMID 36793341, 2022). "The NB5 assay uses RT-PCR to detect the co-expression of five mRNAs from the neuroblastoma-associated genes, CHGA, DCX, DDC, PHOX2B, and TH." (PMID 34055604, 2021). "Up-regulation of miR-128 inhibited Reelin and DCX expression and then reduced neuroblastoma cell notility and invasiveness." (PMID 28146425, 2017). "Exposure to bone morphogenetic protein (BMP)-4 was found to enhance a TrkAhigh/CD15−/CD184− neuroblastoma cellular subset, accompanied by a reduction in doublecortin-positive neuroblasts and of NMYC protein expression in SH-SY5Y cells." (PMID 29051534, 2017). "Moreover, miR-128 upregulation inhibits Reelin and DCX expression leading to impairment of neuroblastoma cell motility and invasiveness." (PMID 32993809, 2020). "In rat neuroblastoma cells the phosphorylated FIGQY-domain of neurofascin is bound by doublecortin." (PMID 19320973, 2009). "Irrespective of a direct role of DCX in NB cell motility, the present data suggest that the detection of DCX+ cells in untreated and treated tumors in neuroblastoma affected patients may be prognostic of tumor aggressiveness, as well as of a severe tumor relapse after treatment." (PMID 18230156, 2008). "Gene expression analysis of NSs by quantitative polymerase chain reaction (qPCR) of β-catenin, NeuroD1, SOX2, Nestin, β-tubulin 3, and DCX genes was compared between each group and the SHSY-5Y neuroblastoma (positive control for neuronal cells)." (PMID 36835256, 2023). "High levels of DCX, PHOX2B, or TH mRNAs in BM and PB samples at diagnosis or BM samples after induction therapy predicted poor outcome in children with stage 4 neuroblastoma." (PMID 31214500, 2019). "The combined signature of five markers (CHGA, DCX, DDC, PHOX2B, and TH) expression in BM and PB was correlated with PFS of relapsed/refractory neuroblastoma." (PMID 31214500, 2019). "A set of three markers (DCX, PHOX2B, TH) was identified by genome-wide gene expression microarray analyses of 32 neuroblastoma tumors and pooled PB sample from 24 healthy volunteers followed by selecting genes not expressed in pooled PB samples." (PMID 31214500, 2019). "DCX expression is also detectable in some tumors of the nervous system, such as GBM and neuroblastoma." (PMID 24555688, 2014). "In the present study we have analysed by immunofluorescence (IF) the presence of DCX and LIS1 in the different cell subtypes that constitute the SK-N-SH neuroblastoma cell line." (PMID 18230156, 2008). "Nevertheless, no information is available on the expression of doublecortin in the different cell-types composing human neuroblastoma, its correlation with neuroblastoma cell motility and invasiveness, and the possible modulations exerted by retinoic acid treatment." (PMID 18230156, 2008).
band heterotopia (16 papers, 2008 to 2024). "Mosaic pathogenic variants in the DCX gene are associated with milder presentation and mainly seen in individuals with subcortical band heterotopia." (PMID 35888005, 2022). "Pathogenic variants in the DCX gene have typically been associated with X-linked subcortical laminar or band heterotopia in females and more severe X-linked lissencephaly in males." (PMID 35888005, 2022). "Subcortical band heterotopia (SBH) is a rare neurodevelopmental disorder due to mutation in the DCX or LIS1 gene." (PMID 34540393, 2021). "On the other hand, DCX was discovered in a screen of patients with subcortical band heterotopia and X-linked lissencephaly." (PMID 29180624, 2017). "Mutations in DCX induce marked migration defects in humans leading to subcortical band heterotopia (SBH, ‘double cortex’ syndrome) in females and to the more severe lissencephaly (‘smooth brain’ syndrome) in males." (PMID 25881110, 2015). "More than 90% of patients with subcortical band heterotopia are female and the cause is usually heterozygous DCX mutation." (PMID 26052266, 2015). "Both these genes are associated with Lissencephaly 1 and Subcortical Laminar Heterotopia, with autosomal dominant inheritance for PAFAH1B1 (OMIM#607432), and with X-Linked inheritance for DCX (MIM#300067)." (PMID 38790177, 2024).